INS (insulin)
Diseases named in the same sentence as INS in open-access papers (continued):
Sharing a sentence is not in itself a finding about the gene and the disease.
Obesity (continued). "These isozymes are implicated in the comorbidities associated with obesity through NO production, which has essential functions including regulating adiposity, energy expenditure, and insulin sensitivity." (PMID 37371984, 2023). "Obesity is a well-known risk factor for DM, and lipid accumulation in patients with DM impairs insulin signaling and reduces glucose uptake." (PMID 37538973, 2023). "It has been reported that obesity is associated with dysregulation in sphingolipid metabolism, particularly ceramides, and insulin resistance in tissues such as adipose tissue, liver, and skeletal muscle." (PMID 38139843, 2023). "These include lower plasma glucose, improved insulin sensitivity, and reduced susceptibility to obesity and its comorbidities." (PMID 36807778, 2023). "Among these, six metabolites were associated with measures of obesity and adiposity (BMI and leptin) and nine metabolites with parameters of the glucose-insulin axis (glucose, C-peptide, ISHOMA)." (PMID 37029207, 2023). "The insulin sensitizing effect of ILK deletion is also associated with improved hepatic steatosis in obesity." (PMID 37383542, 2023). "A recent review summarized that combined exercise improves glycemic control, weight loss, and insulin sensitivity among patients with type 2 diabetes and concurrent overweight/obesity." (PMID 37900128, 2023). "DM can result from either insufficient insulin production (type 1DM) or a deficiency in insulin action due to obesity and lifestyle changes (type 2DM)." (PMID 37513920, 2023). "Obesity is strongly associated with the development of type 2 diabetes (T2DM): the insulin-resistance state demands an increase in insulin delivery to the liver, muscle, and adipose tissue to maintain euglycemia." (PMID 38138997, 2023). "Mice with myocyte-specific SEL1L deficiency exhibit enhanced insulin sensitivity, increased adipose beigeing, and resistance to diet-induced obesity." (PMID 37535424, 2023). "Since Fabp4–/– mice are also protected against obesity-associated hyperinsulinemia, the decrease in lipolysis-driven insulin secretion has been considered as one potential contributing factor to their reduced hyperinsulinemia and improved metabolic health." (PMID 37279064, 2023). "Such an increase in obesity is associated with increased inflammation, disturbance of lipid metabolism, increased blood pressure, decreased insulin sensitivity and, consequently, a higher risk for diabetes 2, and CVD events." (PMID 38248879, 2023). "Obesity-associated inflammation can impair insulin signaling through serine phosphorylation of insulin receptor substrate-1 (IRS-1) and inhibiting phosphatidylinositol 3-kinase (PI3K)/protein kinase B (PKB) signaling, resulting in impaired glucose uptake." (PMID 37424869, 2023). "Previous studies have also found that high-fat-fed Nrg-4 knockout mice have higher plasma TG concentrations, higher FPG and plasma insulin levels, suggesting that Nrg-4 deficiency can lead to glucose tolerance after diet-induced obesity." (PMID 36915073, 2023). "Equine Metabolic Syndrome, a disorder associated with insulin dysregulation, obesity and dyslipidemia is more prevalent in overweight horses, often culminating with the devastating hoof condition, laminitis." (PMID 36830453, 2023). "In the fat body, it has been shown under high fat diet induced obesity, that fat body derived Gbb can cause insulin resistance via negative regulation of the insulin signalling pathway." (PMID 38014610, 2023). "In turn, the inhibition of DNA efflux from mitochondria into the adipocyte cytosol reduces obesity-associated inflammation and insulin resistance." (PMID 37830559, 2023). "Obesity causes regulatory disturbances in many metabolic pathways including carbohydrate metabolism, and especially insulin." (PMID 37432262, 2023). "This review explores the complex relationships among age-associated obesity, the insulin–leptin axis, and the Cdc42 signaling pathway." (PMID 38068822, 2023).
Obesity (continued). "GH has been demonstrated to increase metabolic rate and improve insulin sensitivity, thereby regulating blood glucose levels and reducing the risk of developing obesity-related health complications, including T2DM." (PMID 37298507, 2023). "Despite both men and women are influenced by the obesity load, women showed increased CVDs risk, specifically when overweight/obese and insulin resistant." (PMID 37580741, 2023). "The insulin/IGF-1 axis is associated with obesity-induced prostate carcinogenesis via the phosphatidylinostitol-3 kinase (PI3K)/Akt/mTOR pathways." (PMID 36755926, 2023). "Research also indicates that adipose tissue is a target tissue of ADPN, which increases insulin sensitivity and resists macrophage infiltration and inflammatory factor expression caused by obesity." (PMID 36997952, 2023). "Numerous in vivo studies have further proven the link between obesity and cognitive delay, involving the underlying biological mechanism related to insulin resistance, leptin, increased fat mobilization, brain-derived neurotrophic factor (BDNF), and cytokines." (PMID 37627544, 2023). "RIP3 and pMLKL are induced in visceral white adipose tissue (WAT) in patients with obesity and are positively associated with body mass index and perturbed metabolic serum markers, such as HbA1c and insulin." (PMID 38161978, 2023). "Current understanding of the complex signaling pathways underlying the obesity/T2D/BCa link focuses particularly on the insulin/IGF system." (PMID 36729355, 2023). "In pediatric patients with obesity, a decreased insulin sensitivity was associated with the activation of the inflammasomes–cytosolic protein complexes involved in innate immune system activation." (PMID 36670674, 2023). "It significantly depends on the physiological parameters, weakens with obesity and MS, and increases with inflammatory diseases and insulin-deficient forms of DM, although the mechanisms in each case differ and are not always investigated." (PMID 36834685, 2023). "The improved islets function of the pancreas with weight loss and the worsened function during weight gain show that obesity impacts the ability to secrete insulin." (PMID 36975496, 2023). "The main purpose of the study is to assess the association between obstructive sleep apnea (OSA) and insulin secretion in children with obesity." (PMID 36670156, 2023). "Endocrine biomarkers associated with maternal obesity included leptin, insulin, thyroid stimulating hormone, adiponectin, progesterone, free T4 and human chorionic gonadotropin." (PMID 36520252, 2023). "Obesity is a metabolic state of energy excess associated with systemic alterations in host physiology including hormone dysregulation, insulin resistance, inflammation, and microbial dysbiosis." (PMID 37648285, 2023). "The pathophysiology of T2D with obesity as the dominant risk factor is mainly characterized by insulin resistance in peripheral organs and the insufficient secretion of insulin from pancreatic β-cells." (PMID 37863964, 2023). "SLC38A8 has a high GWAS Catalog score (14.1) with adiponectin measurement, which directly affects insulin sensitivity and obesity, and a strong association with eye diseases, e.g. foveal hypoplasia 2 and anterior segment dysgenesis." (PMID 37205363, 2023). "Since sedentary lifestyles are an important cause of obesity and T2DM, and exercise can improve insulin sensitivity and attenuate fat accumulation in the liver, increasing physical activities would be an effective intervention to combat obesity and T2DM." (PMID 36836874, 2023). "In individuals with obesity and T2D, a substantial and sustained weight loss can result in T2D remission, through improved insulin sensitivity and β-cell recovery." (PMID 38026205, 2023).
Obesity (continued). "While adipocyte-specific Slc35d3 knockin is protected against diet-induced obesity, adipocyte-specific Slc35d3 knockout inhibits white adipose tissue browning and causes decreased energy expenditure and impaired insulin sensitivity in mice." (PMID 37996411, 2023). "Studies to date have suggested that prenatal MHF is associated with increased BP, insulin mesenteric, dyslipidemia, obesity, and endothelial dysfunction in adult offspring." (PMID 36615902, 2023). "The association between obesity and tumorigenesis has been attributed to chronic low-grade inflammation, elevated levels of growth factors, insulin, and insulin-like growth factor-1." (PMID 37777736, 2023). "Bariatric surgery is known to improve metabolic parameters and decrease the risk of NAFLD in individuals with severe obesity, which is largely attributed to the substantial weight loss, enhanced insulin sensitivity, and reduced inflammation following surgery." (PMID 37375574, 2023). "That means that higher DNA methylation in the ROI of the Slc2a4 is associated with obesity-related parameters of increased body weight, plasma insulin levels, and blood glucose levels." (PMID 37047391, 2023). "Type 2 diabetes (T2D) is a chronic metabolic condition associated with obesity, oxidative stress-mediated inflammation, apoptosis, and impaired insulin signaling." (PMID 37762060, 2023). "In fact, in adipose tissue, the M1 macrophages secrete high levels of pro-inflammatory cytokines (TNF-α, IL-6 and IL-1β), inducing an inflammation state and an impairment of insulin sensitivity, typically associated with obesity." (PMID 37447161, 2023). "Age, educational level, insulin prescription, hypertension and obesity were positively associated with participation in follow-up care." (PMID 37758812, 2023). "Through using elevated fasting plasma LDL cholesterol, low HDL cholesterol, elevated blood glucose, and elevated insulin levels as risk factors, these findings support the association between obesity and cardiovascular risk." (PMID 37686748, 2023). "Increased levels of adiponectin are also associated with increased insulin sensitivity and general anti-inflammatory reactions for many inflammatory conditions in addition to obesity, such as asthma and inflammatory bowel disease." (PMID 37113754, 2023). "There is a parallel between PTSD and obesity, as low adiponectin levels correlate with obesity, and weight loss is associated with increased levels and improved insulin sensitivity." (PMID 37374323, 2023). "In summary, our findings provide insights into the effects of lifestyle intervention on branched‐chain amino acid‐related metabolites and their associations with insulin sensitivity in adolescents with obesity." (PMID 36415168, 2023). "An insult or injury (i.e., autoimmunity, obesity, toxin, trauma, stress etc.)causes inflammation in the pancreas that disrupts normal pancreatic insulin rhythmicity." (PMID 37446104, 2023). "Due in part to an increase in the influx of fatty acids and a buildup of ceramides, obesity causes the dysregulation of various cell‐intrinsic pathways, which in turn impairs the transmission of insulin signalling molecules." (PMID 36952350, 2023). "Insulin sensitivityprotects the heart from obesity-associated cardiovascular disease, increasing fatstorage in adipose tissue, and preventing lipid spillover into insulin-sensitivetissues, such as the liver and muscle." (PMID 36544807, 2023). "A lot of evidence shown that when DM occurs, it tends to cause a series of symptoms such as obesity, insufficient insulin secretion, inflammation, elevated cholesterol, and hardened blood vessels." (PMID 36646777, 2023). "Particularly in women with PCOS, a condition often associated with obesity and infertility, lifestyle changes have been shown to restore reproductive potential by enhancing insulin sensitivity and regulating luteinizing hormone levels." (PMID 38264286, 2023).
Obesity (continued). "Obesity, metabolic complications, and COVID-19 severity were all linked, with a focus on fat mass distribution and insulin resistance." (PMID 37796879, 2023). "Metformin, a first-line medication for type 2 diabetes associated with obesity, lowers blood sugar levels, reduces inflammation, improves insulin sensitivity, and improves endothelial function in rodents and humans." (PMID 37759984, 2023). "The pathophysiology underlying the obesity–breast cancer link is complex and multifactorial, involving mechanisms associated with increased circulating insulin and glucose, altered levels of adipokines and estrogen signaling, and chronic inflammation." (PMID 37173991, 2023). "Aging is a risk factor for obesity due to declines in metabolic fitness and insulin signaling, while obesity itself accelerates the aging process and increases the severity of geriatric syndromes." (PMID 36287320, 2023). "Native ponies are at increased risk of obesity and metabolic perturbations, such as insulin dysregulation (ID), a key risk factor for endocrinopathic laminitis." (PMID 37824555, 2023). "Under conditions of obesity, loss of insulin sensitivity in adipocytes results in unsuppressed lipolysis, which leads to increased levels of hormonal FABP4." (PMID 37172691, 2023). "Previously, using an Ossabaw swine model, our group has shown that diet-induced obesity is associated with brain insulin resistance, evidenced by decreased insulin-stimulated Akt signaling in prefrontal cortex (PFC) of pigs fed a Western diet (WD)." (PMID 38163062, 2023). "Our results show that obesity is associated with decreased insulin sensitivity in the three tissues since the incubation of explants with insulin did not activate the PI3K/Akt pathway." (PMID 37239868, 2023). "Due to the fact that human MAPK3 is a common target for both obesity and DM, and is linked with the insulin signaling pathway, we report the virtual screening of the JME phytocompounds as novel potential inhibitors of human MAPK3 in this work." (PMID 36716329, 2023). "Among others, two pathways seem especially essential in the CRC–obesity association—the insulin/insulin-like growth factor axis and PI3K/Akt." (PMID 37048534, 2023). "The KD was also associated with lower fasting serum insulin levels in women with obesity and ovarian or endometrial cancer, as suggested by the authors, to enhance insulin sensitivity." (PMID 37155645, 2023). "Phospholipid metabolites have been identified as potential biomarkers for obesity-associated insulin sensitivity." (PMID 36398677, 2023). "It is commonly accepted that obesity is highly associated with insulin insensitivity in patients with type 2 diabetes (T2D)." (PMID 37373436, 2023). "T2D, insulin and obesity were found among the top shared risk factors, along with lipids and vitamin D. Top outcomes included T2D, CVD, COVID-19 and Alzheimer’s disease." (PMID 37751957, 2023). "Obesity is a rising concern among horses as it is associated with metabolic disorders such as insulin imbalances, high lipid levels, and laminitis." (PMID 37104445, 2023). "In experimental animal models, SCFA supplementation reduces body weight, improves insulin sensitivity, and reduces obesity-associated inflammation." (PMID 37620311, 2023). "Consumption of dietary MUFAs has been associated with improved blood lipid profiles, blood pressure, insulin sensitivity, and blood glucose levels, as well as overall decreased risk of obesity." (PMID 37396963, 2023). "Obesity causes hypothalamic–pituitary–adrenal dysregulation and changes in the plasma levels of cortisol, leptin, adiponectin, resistin, and insulin, which are hormones involved in emotional and mood regulation." (PMID 37046297, 2023). "Spearman’s correlation analysis for the association of obesity with insulin secretion and sensitivity." (PMID 36909323, 2023).
Obesity (continued). "It is well appreciated that excessive circulating insulin (i.e., hyperinsulinemia) is associated with body fat accumulation and obesity via inhibiting lipolysis as well as promoting lipogenesis in adipocytes." (PMID 37176545, 2023). "These depots are thought to be important for muscle contraction during physical exercises and to be associated with the impaired insulin sensitivity in patients with obesity and/or T2DM, as well as in elderly and sedentary individuals." (PMID 37374197, 2023). "Breast cancer is the most common malignancy in women, and it is linked to several risk factors including genetic alterations, obesity, estrogen signaling, insulin levels, and glucose metabolism deregulation." (PMID 37361518, 2023). "Another mechanism is that obesity, especially when combined with physical inactivity, causes a decreased tissue response to insulin, notably in terms of glucose absorption." (PMID 36928374, 2023). "Insulin resistance and insulin insensitivity in muscles leads to hyperinsulinemia caused by obesity." (PMID 38089929, 2023). "Obviously, this can be linked to the higher weight and BMI of our study population at baseline since obesity has been extensively regarded as a direct cause of β-cell damage and impaired insulin sensitivity." (PMID 37552330, 2023). "Some studies have also demonstrated that the offspring of mothers with GDM have a heightened susceptibility to obesity, T2D, and/or impaired insulin sensitivity and secretion." (PMID 38137473, 2023). "The structural and functional changes of the intima, middle layer and outer layer of the vasculature are the main causes of arterial stiffness in patients with obesity, which can be regulated by plasma factors such as aldosterone and insulin." (PMID 36894988, 2023). "In summary, obesity’s association with AD involves complex interactions such as leptin resistance, insulin dysfunction, altered glucose metabolism, oxidative stress, amyloid-beta disturbances, and brain atrophy." (PMID 38026693, 2023). "Overall, genetic variation in target(s) of thiazolidinediones, of sulfonylureas, and of insulin and its analogues demonstrated associations with higher risk of obesity-related phenotypes." (PMID 37052755, 2023). "Obesity affects cardiac geometry, causing both eccentric (due to increased cardiac output) and concentric (due to insulin resistance) remodelling." (PMID 36761185, 2023). "Obesity alters the function of the hypothalamic-pituitary axis, which is associated with high levels of insulin, androgen, and estrogen and is involved in the impairment of ovarian folliculogenesis." (PMID 38047110, 2023). "Of particular interest, Plin5-Tg mice were protected from diet-induced obesity in association with improved insulin sensitivity and glucose tolerance." (PMID 37150323, 2023). "mRNAs of PPAR‐γ and as well, FOXO1, FOXO3 and PTEN are targets of miR‐320a and miR‐486‐5p, respectively, and are associated to insulin metabolism and related conditions such as obesity and dyslipidemia." (PMID 37329278, 2023). "Another example is adipocyte associated pyruvate carboxylase interacting lncRNA (ADIPINT), whose expression is increased in obesity and linked to fat cell size, adipose insulin resistance, and pyruvate carboxylase activity." (PMID 36672953, 2023). "Network analysis associates fatty acid metabolism and basal insulin secretion with hyperglycemic-obesity, while expression of Pdyn and hypoxia response is associated with normoglycemic-obesity." (PMID 36978008, 2023). "In conclusion, higher tertiles of the MIND diet score were associated with increased insulin sensitivity and reduced stress among individuals with obesity significantly." (PMID 36726099, 2023). "Ingestion of sweetened condensed milk that contains 53% sucrose, and causes a rapid increase in plasm insulin levels, induces energy storage as fat in the adipose tissue, which is directly associated with the development of obesity." (PMID 37894869, 2023).